CTC1 (CST telomere replication complex component 1)
Description:
Component of the CST complex proposed to act as a specialized replication factor promoting DNA replication under conditions of replication stress or natural replication barriers such as the telomere duplex. The CST complex binds single-stranded DNA with high affinity in a sequence-independent manner, while isolated subunits bind DNA with low affinity by themselves. Initially the CST complex has been proposed to protect telomeres from DNA degradation. However, the CST complex has been shown to be involved in several aspects of telomere replication. The CST complex inhibits telomerase and is involved in telomere length homeostasis; it is proposed to bind to newly telomerase-synthesized 3' overhangs and to terminate telomerase action implicating the association with the ACD:POT1 complex thus interfering with its telomerase stimulation activity. The CST complex is also proposed to be involved in fill-in synthesis of the telomeric C-strand probably implicating recruitment and activation of DNA polymerase alpha. The CST complex facilitates recovery from many forms of exogenous DNA damage; seems to be involved in the re-initiation of DNA replication at repaired forks and/or dormant origins. Involved in telomere maintenance. Involved in genome stability. May be in involved in telomeric C-strand fill-in during late S/G2 phase (By similarity).
Synonyms: C17orf68; FLJ22170; AAF132; AAF-132; CRMCC; tmp494178
Tractability: Small molecule: a structure with a bound ligand is known. PROTAC: ubiquitination databases record sites on it; its protein half-life has been measured.
Gene: Protein-coding gene on chromosome 17 (8,224,815 to 8,248,058, reverse strand). Ensembl gene ENSG00000178971.
Subcellular location: Nucleus; Chromosome, telomere
Subcellular location (Human Protein Atlas): Nucleoplasm; Cytosol
Pathways (Reactome):
Cell Cycle: Polymerase switching on the C-strand of the telomere; Telomere C-strand synthesis initiation
Gene Ontology:
Molecular function: G-rich strand telomeric DNA binding; protein binding; telomeric DNA binding; single-stranded DNA binding
Biological process: negative regulation of telomere maintenance via telomerase; telomere maintenance; positive regulation of DNA replication; telomere capping; telomere maintenance via telomere lengthening
Cellular component: chromosome, telomeric region; CST complex; nucleoplasm; nucleus
Genetic constraint (gnomAD): Loss-of-function variants: 86 observed, 132.59 expected, observed/expected ratio (o/e) 0.65, 90% interval 0.54 to 0.78. The upper end of that interval is the gene's LOEUF score, 0.78, which puts it in group 3 of 6, group 1 being the genes least tolerant of losing a copy. Missense variants: 1,371 observed, 1,486.8 expected, observed/expected ratio (o/e) 0.92, 90% interval 0.88 to 0.96. Synonymous variants: 585 observed, 613.7 expected, observed/expected ratio (o/e) 0.95, 90% interval 0.89 to 1.02.
Gene-disease validity (ClinGen):
ClinGen rates the evidence that CTC1 causes each of these diseases.
cerebroretinal microangiopathy with calcifications and cysts 1 (autosomal recessive): Definitive.
Homologues: Orthologues: macaque CTC1 (95% identical), chimpanzee CTC1 (91% identical), pig CTC1 (77% identical), rabbit CTC1 (76% identical), dog CTC1 (73% identical), guinea pig CTC1 (72% identical), mouse Ctc1 (69% identical), rat Ctc1 (68% identical), tropical clawed frog ctc1 (30% identical), zebrafish ctc1 (28% identical).
Diseases named in the same sentence as CTC1 in open-access papers:
CTC1 is named in the same sentence as 51 diseases in open-access papers, as found by Europe PMC text mining. Sharing a sentence is not in itself a finding about the gene and the disease. The quoted sentences say what the papers report.
Coats plus syndrome (18 papers, 2013 to 2025). "Variants in the CTC1 gene are associated with Coats plus syndrome, as well as cerebroretinal microangiopathy with calcifications and cysts." (PMID 36077770, 2022). "CTC1 and STN1 mutations have been implicated in the telomere-related Coats Plus syndrome and patients with CTC1 mutations exhibit telomere dysfunction that is consistent with telomeric DNA replication errors." (PMID 33869233, 2021). "A genetic test confirmed the presence of CTC-1 gene mutation, which results in Coat's plus syndrome." (PMID 31874382, 2019). "Since its initial identification, more than 20 recessive mutations associated with CRMCC/Coats plus syndrome and DC phenotype have been described in the CTC1 gene." (PMID 25928698, 2015). "Cerebroretinal Microangiopathy with Calcifications and Cysts (CRMCC) is one of the rare telomeropathies caused by a variant in one of the telomere maintenance genes called conserved telomere maintenance component 1 (CTC1)." (PMID 40440483, 2025). "The presence of subcortical cysts is suggestive of a diagnosis of LCC due to compound heterozygous variants in the SNORD118 gene, or of Coats plus syndrome (cerebroretinal microangiopathy) due to mutations in the conserved telomere maintenance component 1 (CTC1) gene." (PMID 37240341, 2023). "Coat plus syndrome is reported with obvious inherited tendency and earlier onset age, and patients usually present with typical retinal angioma; genetic analysis revealed a mutation in the CTC1 gene." (PMID 28723803, 2017). "Also, Coats plus syndrome has recently been associated with mutations in the CTC1 gene that is related to telomeric function." (PMID 26852234, 2016). "Coats plus syndrome, cerebroretinal microangiopathy with calcifications and cysts (CRMCC), is a rare disease with an autosomal recessive pattern caused by a mutation in the encoding conserved telomere maintenance component 1 (CTC1) gene." (PMID 35260125, 2022). "Several studies have reported that biallelic pathogenic variants in CTC1 and STN1 are implicated in the development of Coats plus syndrome and, in rare instances, dyskeratosis congenita." (PMID 39198715, 2024). "This study provides a valuable direction to understand the molecular basis of CTC1 dysfunction in disease progression, including Coats plus syndrome." (PMID 33986331, 2021). "Coats plus syndrome, cerebroretinal microangiopathy with calcifications and cysts, is a rare disease with autosomal recessive pattern occurring due to a mutation in CTC1, encoding conserved telomere maintenance component 1, gene." (PMID 35260125, 2022). "Recently, identification of biallelic mutations in the CTC1 gene in the vast majority of patients with Coats plus syndrome but in none with LCC provides strong evidence that the two conditions are genetically distinct entities." (PMID 23742313, 2013). "Mutations in the telomere maintenance complex (the CST complex; CTC1, STN1, and TEN1) lead to cerebroretinal microangiopathy (Coats plus syndrome) with a failure of multiple organs." (PMID 34139671, 2021). "The lack of a mutation in the CTC1-gene in cases of LCC and its manifestation only in the central nervous system are currently regarded as the main features distinguishing Coats plus syndrome from LCC." (PMID 26852234, 2016).
dyskeratosis congenita (13 papers, 2013 to 2025). Dyskeratosis congenita (DC) is a rare ectodermal dysplasia that often presents with the classic triad of nail dysplasia, skin pigmentary changes, and oral leukoplakia associated with a high risk of bone marrow failure (BMF) and cancer. "Since then, a spectrum of phenotypes, including bone marrow failure, colorectal cancer and dyskeratosis congenita, have also been detected in patients with CTC1 mutations." (PMID 37978541, 2023). "CTC1 mutations were first identified in Coat Plus and dyskeratosis congenita, two types of autosomal recessive disorders that are associated with telomere maintenance defects." (PMID 37978541, 2023). "Several naturally occurring mutations of the CTC1 protein cause Coats plus (CP) syndrome and Dyskeratosis congenita (DC) or bone marrow syndrome." (PMID 33986331, 2021). "Filtering against the public SNP/variant repositories, we identified a host of candidate genes, EPB41L4A and CTC1 associated with colon, neural/brain muscles and Dyskeratosis Congenita maladies." (PMID 29703930, 2018). "In addition, the human disease(s) caused by CTC1 mutations (known as Coats plus or CRMCC) has a phenotypic spectrum that is distinct from the prototypical telomere diseases such as dyskeratosis congenita." (PMID 23300477, 2013). "Mutations in human CTC1 and STN1 have mainly been associated with dyskeratosis congenita and Coats Plus (and references therein)." (PMID 40497960, 2025). "Concerning CST, mutations in human CTC1 and STN1 have been found to be mainly associated with dyskeratosis congenita and Coats Plus (and references therein), as well as several types of cancer." (PMID 40497960, 2025). "Moreover, the mutation in CTC1 caused cancer-prone diseases including Coats plus (CP) or dyskeratosis congenita (DC)." (PMID 33937245, 2021). "Diseases and conditions associated with pathogenic variants of CTC1 include cerebroretinal microangiopathy with calcifications and cysts (CRMCC) and dyskeratosis congenita (DC)." (PMID 30393977, 2018). "Telomeropathies include dyskeratosis congenita (DKC), in which a disease-causing variant is often found within the dyskerin (DKC1) gene on the X chromosome or other telomere maintenance genes such as TINF2, TERC, TERT, CTC1, and other genes." (PMID 40440483, 2025). "Mutations in CTC1 and STN1 are associated with two congenital genetic disorders, namely Coats plus (CP) syndrome (also known as cerebroretinal microangiopathy with calcifications and cysts) and dyskeratosis congenita (DKC)." (PMID 34283091, 2021). "Also, mutations in human CTC1, the ortholog of CDC13, are found in a number of diseases associated with telomere defects (Coats plus, dyskeratosis congenita and CRMCC); however, no equivalent mutations in STN1 or TEN1 have yet been identified in the same cohorts of patients." (PMID 24835988, 2014).
melanoma (5 papers, 2014 to 2025). A malignant, usually aggressive tumor composed of atypical, neoplastic melanocytes. "In this study, to the best of our knowledge, we demonstrate for the first time that CTC1 expression is associated with radioresistance in human melanoma cells." (PMID 24718655, 2014). "High levels of CTC1 seem to be directly associated with radioresistance in human melanoma cell lines as an independent predictive factor." (PMID 24718655, 2014). "In this study, by establishing a radiosensitive/radioresistant human melanoma cell model, MDA-MB-435/MDA-MB-435R, we aimed to investigate the association of CTC1 expression with radiosensitivity in human melanoma cell lines, and to elucidate the possible underlying mechanisms." (PMID 24718655, 2014). "In a human melanoma cell model, downregulation of CTC1 enhances the radiosensitivity by inducing DNA damage and promoting telomere shortening, thus making it an attractive target for the treatment of human melanoma." (PMID 33043007, 2020). "Our results demonstrated that the knockdown of CTC1 increased the rate of apoptosis in both melanoma cell lines." (PMID 24718655, 2014). "By establishing a radiosensitive-radioresistant human melanoma cell model, we found that CTC1 enhances the radioresistance of human melanoma cells by inhibiting telomere shortening and apoptosis." (PMID 24718655, 2014). "Our data demonstrate that CTC1 expression is markedly decreased in the radiosensitive melanoma cells compared with the radioresistant cells." (PMID 24718655, 2014). "Taken together, our findings suggest that CTC1 increases the radioresistance of human melanoma cells by inhibiting telomere shortening and apoptosis." (PMID 24718655, 2014). "In a similar study, it has been reported that CTC1 could be used as an independent predictive factor, as its upregulation prevented telomere shortening and increased radioresistance in melanoma cells." (PMID 36233645, 2022). "Moreover, the knockdown of CTC1 imparts radiosensitivity to human melanoma cells by enhancing telomere shortening and inducing cell apoptosis." (PMID 24718655, 2014). "However, the role of human CTC1 in the response of melanoma cells to ionizing radiation remains unknown." (PMID 24718655, 2014). "Thus, we infer that the knockdown of CTC1 may act as a potent radiosensitizer in human melanoma cell lines." (PMID 24718655, 2014). "Thus, CTC1 may be an attractive target gene for the treatment of human melanoma." (PMID 24718655, 2014).
bone marrow failure (2 papers, 2020 to 2021). "Germline CTC1 mutation has also been observed in DC and acquired bone marrow failure patients." (PMID 33937245, 2021).
calcification (2 papers, 2018 to 2022). Process by which organic tissue becomes hardened by the physiologic deposit of calcium salts. "Cerebroretinal microangiopathy with calcifications and cysts (CRMCC) is an autosomal recessive disorder caused by pathogenic variants of the conserved telomere maintenance component 1 (CTC1) gene." (PMID 30393977, 2018).
Coats disease (2 papers, 2022 to 2025). Coats disease (CD) is an idiopathic disorder characterized by retinal telangiectasia with deposition of intraretinal or subretinal exudates, potentially leading to retinal detachment and unilateral blindness. "Within the CST complex, mutations in CTC1 and STN1 have been established as contributors to ocular manifestations, such as exudative retinopathy and retinal telangiectasia, which have been frequently observed." (PMID 40215293, 2025). "LCC is distinguishable from Coats disease, another IWMD with similar presentations, as mutations in the conserved telomere maintenance component 1 (CTC1) had been found causal to Coats disease but not LCC." (PMID 35389826, 2022).
glioma (2 papers, 2015 to 2024). A benign or malignant brain and spinal cord tumor that arises from glial cells (astrocytes, oligodendrocytes, ependymal cells). "The significant association between glioma risk and common LTL-associated variants in CTC1 and OBFC1 is particularly intriguing in light of a recent report demonstrating that germline loss-of-function mutations in shelterin-complex genes are a rare cause of familial oligodendroglioma." (PMID 26646793, 2015). "We found significant differences in the expression levels of ADD2, CTC1, SRCIN1, RORA, and ULK2 genes in gliomas of different grades, excluding VPS4A." (PMID 39698112, 2024). "Furthermore, survival analysis revealed that patients with glioma with high expression of ADD2, CTC1, SRCIN1, VPS4A, ULK2, excluding RORA, had a longer overall survival than those with low expression." (PMID 39698112, 2024). "Similarly, disease-free survival was found to be longer in patients with glioma with high expression of ADD2, CTC1, SRCIN1, RORA, VPS4A, and ULK2 than in those with low expression." (PMID 39698112, 2024).
leukemia (2 papers, 2022 to 2023). A malignant (clonal) hematologic disorder, involving hematopoietic stem cells and characterized by the presence of primitive or atypical myeloid or lymphoid cells in the bone marrow and the blood. "Beyond hTERT, B-ALL patients also show high expression of CTC1 and OBFC1 (they are part of CST complex which works with the shelterin complex to lengthen telomeres); however, only CTC1 was associated with leukemia." (PMID 36980962, 2023). "CTC1 expression was induced 14.6 (3.00 × 10−4) and 2.8 (p = 0.040) folds in pediatric and adult leukemia cases." (PMID 36233645, 2022). "Although CTC1 and OBFC1 are the components of the same complex, their different association with ALL disease suggests their non-telomeric role in leukemia as well." (PMID 36233645, 2022).
Osteopenia (2 papers, 2022 to 2024). Osteopenia is a term to define bone density that is not normal but also not as low as osteoporosis. "Coats plus syndrome (OMIM #612199) is a rare AR disease due to pathogenic variants in the CTC1 gene, with cerebroretinal microangiopathy, intracranial calcifications, brain cysts, leukodystrophy, osteopenia, bone fractures and poor bone healing and gastrointestinal bleeding." (PMID 35328050, 2022).
progeria (2 papers, 2018 to 2025). "CTC1 pathogenic variants can present with unusual manifestations of progeria accompanied with recurrent bone fractures." (PMID 30393977, 2018).
telomere syndrome (2 papers, 2018 to 2021). Accelerated aging syndromes often caused by inheritable gene mutations resulting in decreased telomere lengths. "CST is encoded by CTC1, STN1 and TEN1 in human cells and mutations in CTC1 and STN1 are associated with Coats plus disease, one of the heritable telomere syndromes." (PMID 30067734, 2018).
uterine carcinosarcoma (2 papers, 2021 to 2022). A usually aggressive malignant neoplasm arising from the uterine corpus and less often the cervix. "TCGA expression analysis reveals that CTC1 mutation or CTC1 downregulation is highly associated with adrenocortical carcinoma, kidney chromophobe, rectum adenocarcinoma, uterine carcinosarcoma, and some other types of cancer formation." (PMID 33937245, 2021).
adrenocortical carcinoma (1 paper, 2021). "Here, we observed that CTC1 expression was negatively associated with miR-376a-3p in adrenocortical carcinoma patients and that the overall survival is dramatically decreased with low CTC1 levels, suggesting that miR-376a-3p may stimulate adrenocortical carcinoma by targeting CTC1." (PMID 33937245, 2021).
fracture (1 paper, 2022). "Similarly, patients with premature ageing through mutation of CTC1 (conserved telomere maintenance component 1) which leads to genome-wide DNA damage and presumably high senescence burden have elevated risk of atypical bone fracture." (PMID 35388291, 2022).
rectum adenocarcinoma (1 paper, 2021). An adenocarcinoma arising from the rectum. "Furthermore, for the clinical patient samples, the high expression of miR-376a was associated with the deregulation of CTC1 and a poor outcome for the rectum adenocarcinoma patients." (PMID 33937245, 2021). "We observed that CTC1 was significantly downregulated in several cancer types, including rectum adenocarcinoma and uterine serous carcinoma." (PMID 33937245, 2021). "Together, our results uncovered a novel role of miR-376a in stimulating rectum adenocarcinoma progression via CTC1 downregulating induced telomere dysfunction." (PMID 33937245, 2021). "Taken together, we identified novel miRNAs which could target CTC1 to promote rectum adenocarcinoma, and our current study provided a detailed mechanism by which telomere function is regulated." (PMID 33937245, 2021). "Moreover, we also observed that the decrease of CTC1 was consistent with the stimulation of miR-376a in the progression of rectum adenocarcinoma." (PMID 33937245, 2021). "Moreover, based on the database analysis and the patient study, we observed that miR-376a-3p may play essential roles in promoting rectum adenocarcinoma progression via downregulating CTC1." (PMID 33937245, 2021).
schizophrenia (1 paper, 2025). A major psychotic disorder characterized by abnormalities in the perception or expression of reality. "One study identified a downregulation of the CST protein CTC1 in individuals with schizophrenia as compared to controls through whole-genome expression profiling." (PMID 40887790, 2025).
skin cutaneous melanoma (1 paper, 2022). "CTC1 mutation predominately occurred in uterine corpus endometrial carcinoma (UCEC) (6.59%), skin cutaneous melanoma (SKCM) (4.91%), and COAD (3.69%)." (PMID 35368664, 2022).
T-cell ALL (1 paper, 2022). "The expression of CTC1, OBFC1, and TERT genes were found to be upregulated in both pediatric and adult B-cell ALL than in T-cell ALL cases but the difference was not statistically significant." (PMID 36233645, 2022).